TRPV1 (transient receptor potential cation channel subfamily V member 1)
Diseases named in the same sentence as TRPV1 in open-access papers (continued):
Sharing a sentence is not in itself a finding about the gene and the disease.
asthma (continued). "Although the contribution of TRPV1 to acidic pH-induced cough and bronchoconstriction is well demonstrated as discussed, it remains to be proven whether TRPV1-mediated neurogenic inflammation plays a central role in asthma and other respiratory diseases." (PMID 25197168, 2014). "Future replication studies could assess whether TRPV1 polymorphisms may be associated with greater cough sensitivity to inhaled capsaicin in cough patients (with and without asthma)." (PMID 22443337, 2012). "In our study, TRPV1 polymorphisms were associated with cough, but only in subjects without asthma." (PMID 22443337, 2012). "TRPV1/TRPA1 mediates the crosstalk between the nervous and immune systems, influencing both acute and chronic symptoms of asthma." (PMID 40678720, 2025). "These inhibit, desensitize, and downregulate TRPV1/TRPA1, which impacts airway inflammation, hyperresponsiveness, and remodeling, ultimately affecting asthma." (PMID 40678720, 2025). "Transient receptor potential channels, specifically vanilloid receptor 1 (TRPV1) and ankyrin 1 (TRPA1), are polymodal sensory channels extensively distributed in the lungs and represent promising therapeutic targets for asthma." (PMID 40678720, 2025). "TRPV1/TRPA1-mediated mechanisms tie tear gas injury to pathways involved in acute/chronic pain, cough, asthma, dermatitis, and neurodegeneration; animal models suggest transient receptor potential inhibitors as potential countermeasures." (PMID 41377027, 2025). "Among TRP channels, TRPA1, TRPV1, and TRPV4 are relevant to asthma due to their widespread expression in the respiratory system." (PMID 39664985, 2024). "Given the complexity and uniqueness of obese asthma, we have identified three TRP channels – TRPV1, TRPM8, and TRPC1 – and examined their role in immune cells, particularly macrophages." (PMID 38365763, 2024). "Several endogenous TRPV1 agonists are present in diseased lungs, such as those affected by COPD and asthma." (PMID 37402746, 2023). "In the later stage, the main components of ACH and BCH will be studied from the level of cells, how to regulate TRPV1 and TAS2R14 to improve calcium homeostasis, and regulation to improve the asthma rat model was further verified." (PMID 36045655, 2022). "Thus, virus-induced rise in intracellular Ca2+ mediated by TRPV1 activation might contribute to the clinical manifestations of asthma, including augmented synthesis and release of TH2 cytokines, mucus overproduction, breakdown in barrier permeability, and increased bronchoconstriction." (PMID 35263387, 2022). "Sensory neurons that express the TRPV1 ion channel are known to mediate AHR in asthma, and activators of TRPV1 induce an increased cough response in COPD patients by activating neuronal TRPV1." (PMID 34071807, 2021). "Considering the fact that the prophylactic administration of antagonists of TRPV1 (AMG9810) and LPA (BrP-LPA) receptors prevents the development of bronchoconstriction, vanilloid receptors can be an important target for asthma therapy." (PMID 34356881, 2021). "Tobacco smokers, patients with asthma, and patients with chronic obstructive pulmonary disease (COPD) have increased responsiveness to TRPV1 agonists citric acid and capsaicin, supporting a role for TRP channels in cough hypersensitivity." (PMID 34557110, 2021). "Clinically, elevation of both pulmonary endogenous TRPV1 stimulants and PGE2 has been believed to be responsible for coughs in patients with asthma, idiopathic pulmonary fibrosis, and COPD." (PMID 33529249, 2021). "In particular, TRP channels showing high levels of expression in sensory neurons such as TRPV1, TRPA1, and TRPM8, have been considered as targets for indications where sensory neurons play a fundamental role, such as pain, itch, and asthma." (PMID 31969645, 2020). "Dual blockade of TRPV1 and LPA receptors with AMG9810 and Brp-LPA reduced the response to asthma plasma by 79 ± 2%." (PMID 30279412, 2018).
asthma (continued). "In the present review, we discuss the roles of ionotropic TRPV1 and ASICs and metabotropic OGR1-family G protein-coupled receptors in the airway inflammation and AHR in asthma and respiratory diseases." (PMID 25197168, 2014). "Thus, it could be hypothesized that genetic variation in TRPV1 increases the risk of an enhanced cough reflex among subjects without asthma." (PMID 22443337, 2012). "This review synthesizes recent mechanistic insights into how dysregulated calcium signaling-via transient receptor potential (TRP) channels (e.g., TRPV1, TRPA1), store-operated calcium entry (SOCE), L-type calcium channels (LTCCs), and mechanosensitive Piezo1-drives key asthma phenotypes." (PMID 41437399, 2025). "This exposure significantly upregulated TRPV1 or TRPA1 in lung tissue, exacerbating asthma-like pathological features, which could be alleviated by using TRPV1 antagonists such as capsazepine or TRPA1 antagonists like HC030031." (PMID 40678720, 2025). "These experimental observations suggest that the activation of TRPV1 and TRPA1 might attenuate Th2 responses and inhibit the progression of airway inflammation, indicating that TRPV1 and TRPA1 may have dual roles in the pathogenesis of asthma." (PMID 40678720, 2025). "Overall, TRP channels, including TRPA1, TRPV1, and TRPV4, contribute to asthma pathophysiology and the immune response by regulating inflammatory processes, immune cell recruitment, and airway remodeling, making them potential therapeutic targets for asthma management." (PMID 39664985, 2024). "TRPV1 is also expressed in non-neuronal areas such as the lung and bladder, affecting the disease progression of cystitis and asthma." (PMID 36615408, 2022). "It is again, however, not clear, in which tissue (neuronal or non-neuronal) TRPV1 is mediating allergic responses to asthma." (PMID 30717260, 2019). "Therefore, TRPA1, TRPV1, and TRPV4 are most promising pharmacological targets for new asthma therapeutics and already effective modulators are ready for use in clinical trials." (PMID 30717260, 2019). "Remarkably, patients that did not respond to standard asthma therapy (i.e., corticosteroids) revealed a significant increase of bronchial TRPV1 expression compared to controls." (PMID 30087301, 2018). "Therefore, how do some CHM metabolites provide therapeutic effects for asthma through TRPV1/TRPA1 activation without inducing asthma symptoms?" (PMID 40678720, 2025). "Thus, viral infection affects TRPV1 expression regardless of the asthma status in children but not in adults." (PMID 39408565, 2024). "Therefore, based on these studies, it is suggested that reduced activation of TRP family channels, especially TRPA1, TRPV1 and TRPV4, may be potential targets for new therapies for asthma." (PMID 37841931, 2023). "This review will focus on TRP channels (TRPA1, TRPC6, TRPV1, and TRPV4), predominantly expressed in non-neuronal lung tissues and their involvement in pathways associated with diseases like asthma, cystic fibrosis, chronic obstructive pulmonary disease (COPD), lung fibrosis, and edema formation." (PMID 30717260, 2019). "However, there is not enough evidence to support this TRPV1 and ROS relationship in allergic asthma, especially in pollutant-promoted asthma." (PMID 28931832, 2017). "Inhibition of TRPA1 alone or TRPA1 and TRPV1 simultaneously shows better effects than the inhibition of TRPV1 alone, suggesting that TRPA1 is more sensitive to the oxidative stress induced by PM2.5 than TRPV1, and that TRPA1 might have a more important role in asthma generation." (PMID 33803491, 2021). "In addition, non-neuronal TRPV1 channels may be involved in airway disorders, and epithelial cells play a significant role in both asthma and COPD." (PMID 27483288, 2016). "However, the role of TRPV1 channel in ASMC proliferation of asthma has not been reported." (PMID 24010863, 2013).
asthma (continued). "Furthermore, sensitization of TRPV1 by inflammatory mediators like prostaglandins (PGs), bradykinin (BK), nerve growth factor (NGF) and LOX metabolites of arachidonic acid may lead to exacerbation of asthma." (PMID 19305794, 2008). "However, expression of TRPV1 on both mRNA and protein level was also found on non-neural cell types and for this reason, recent studies address the role of vanilloid receptor in other inflammatory disorders such as asthma, rheumatoid arthritis or inflammatory bowel diseases." (PMID 31681615, 2019).
colitis (68 papers, 2008 to 2025). Inflammation of the colon. "Three channels TRPA1, TRPM2 and TRPV1 have been shown to influence apoptosis in mice with colitis-associated colon cancer (azoxymethane (AOM)/DSS model)." (PMID 38731999, 2024). "A dinitrobenzene sulfonic acid (DNBS)-induced colitis model revealed severe inflammation in Trpv1−/−-deficient mice, indicating that TRPV1 is required to modulate sensory pathways that regulate the response following the onset of colonic inflammation." (PMID 38731999, 2024). "In particular, TRPV1 gene-deficient mice exhibit less dextran sodium sulphate (DSS)-induced colitis (Refs 31, 32)." (PMID 38659380, 2024). "In experimental colitis animal models, an association has been observed between TRPV1 expression and the occurrence of overactive bladder." (PMID 39544909, 2024). "Previous reports found that during DSS induced colitis, mice with a mutation to constitutively activate TRPV1 showed a significant increase in CD4+ T cells producing IL-17A but not IFNγ." (PMID 38109366, 2023). "We demonstrated that chemogenetic inhibition of TRPV1+ neurons prevents microglial activation associated with VHS in experimental colitis." (PMID 34954381, 2022). "A recent study has shown that TRPV1 deficiency attenuated DSS-induced colitis with reduction in upregulation of SP-positive nerve fibers." (PMID 33251043, 2020). "Here, by using a novel TRPV1 gain-of-function mouse model, we showed that TRPV1 hyperactivation significantly increased susceptibility to DSS-induced colitis." (PMID 33251043, 2020). "To clarify the exact role of TRPV1 in intestinal inflammation, we exploited TRPV1 gain-of-function mutation mice and demonstrated that TRPV1 channel overactivation exacerbated DSS-induced colitis." (PMID 33251043, 2020). "Here, we found that TRPV1 gain of function significantly increased the susceptibility of mice to experimental colitis, and that was associated with excessive recruitment of dendritic cells and enhanced Th17 immune responses in the lamina propria of colon." (PMID 33251043, 2020). "TRPV1 blockade by the non-selective antagonist capsazepine, JNJ 10185734, BCTC and SB366791 in various models of colitis exerted anti-inflammatory actions supporting the pathogenic role of TRPV1 in experimental IBD." (PMID 30935063, 2019). "It is assumed that the augmented nociception to TRPV1 agonists in the colitis model is associated with changes of inflammatory mediators that regulate the activity of nociceptors." (PMID 30087301, 2018). "TRPV1-deficient mice receiving 5% DSS via drinking water developed severe colitis to nearly the same degree as WT mice." (PMID 27356469, 2016). "Attenuation of experimental colitis by capsazepine (CPZ) has long been attributed to its antagonistic action on TRPV1 and associated inhibition of neurogenic inflammation." (PMID 27356469, 2016). "To challenge the mechanism by which CPZ enemas attenuate experimental colitis, we induced dextran sulphate sodium (DSS) colitis in wild-type (WT) and TRPV1-deficient mice (each group n = 8)." (PMID 27356469, 2016). "This contention is also borne out by the observation that the gastroparesis associated with experimental colitis is relieved by TRPV1 blockers." (PMID 21420431, 2011). "Further supporting a role for GPR68 in colitis-associated nociception, we found that Gpr68 expression was enriched in peptidergic subpopulations of colonic sensory neurons and showed high co-expression with Trpv1, a marker of nociceptive afferents." (PMID 41197770, 2025). "In vivo, TRPV1 gain of function causes excessive recruitment of DCs and enhances Th17 immune responses in lamina propria of colon, thereby increasing the susceptibility of mice to experimental colitis." (PMID 36459135, 2023). "Trpv1+ neuron ablation leads to microbial dysbiosis in the mouse colon, and transplantation of the dysregulated microbiota to germ-free mice renders the host susceptible to colitis pathogenesis." (PMID 37336989, 2023).
colitis (continued). "Moreover, compared to wild-type littermates, TRPV1-null mice exhibit more severe LPS-induced sepsis, and more often develop colitis-associated cancer." (PMID 37371563, 2023). "These opposing results may be caused by the different methods used to induce colitis and the non-TRPV1-specific effects of the agonists and antagonists." (PMID 33251043, 2020). "Because Trpv1G564S+/+ mice show mutation of TRPV1 in all cell types, we questioned which cell fraction may render mice more susceptible to colitis." (PMID 33251043, 2020). "Trpa1 and Trpv1 gene deletion decreased dextran sulfate sodium (DSS)-induced colitis severity, as well as Il10−/−-induced spontaneous colitis in Trpv1-deficient mice, whereas Trpv1-deficient mice exhibited more severe colitis in the dinitrobenzene sulfonic acid (DNBS)-induced model." (PMID 32764237, 2020). "Studies with Trpv1 and Trpa1 gene-deficient mice show contradictory data about their roles in colitis, most likely depending on the key pathomechanisms of the different colitis models." (PMID 32764237, 2020). "The mechanisms by which toxin A causes colitis are incompletely known, but it has been shown that there is a neurogenic component involving the transient receptor potential vanilloid type 1 (TRPV1) cation channel expressed by a subset of primary sensory neurons." (PMID 28484490, 2017). "Furthermore, a dinitrobenzene sulfonic acid model causes more severe colitis in TRPV1–/– mice than TRPV1+/+ mice." (PMID 27713376, 2010). "TRPV1 is associated with inducing inflammation and tissue damage in the pancreas, ileum and colon following dextran sulphate sodium-induced colitis in rats, caerulein-induced pancreatitis, Clostridium difficile toxin A- and endocannabinoid-induced colitis." (PMID 19305794, 2008). "Our previous results showed that colonic inflammation caused detrusor instability via activation of transient receptor potential vanilloid 1 (TRPV1) signaling pathways, therefore, we aimed to determine whether neurogenic bladder dysfunction can develop in the absence of TRPV1 receptors." (PMID 23305398, 2013). "The researchers induced colitis-associated colon cancer in mice and showed that the expression levels of the three TRP channels (TRPA1, TRPM2, TRPV1) were overexpressed." (PMID 40813985, 2025). "Capsaicin-induced sensory denervation of TRPV1 was found to result in excessive neutrophil accumulation in a neonatal mouse model of oxazolone-induced colitis." (PMID 38731999, 2024). "As such, in TRPV1- and TRPA1-deficient mice, induced DSS colitis was significantly attenuated compared to wild-type animals." (PMID 38731999, 2024). "In a rat model of TNBS colitis, the combination of TRPV1 antagonist BCTC and TRPA1 antagonist TCS-5861528 was found to significantly reduce visceral hypersensitivity when compared to the injection of the compounds separately, indicating a synergistic effect." (PMID 38731999, 2024). "In the CLP model, similar to the LPS-induced sepsis model, TRPV1 demonstrates anti-inflammatory effects, which contradicts the findings for human models of colitis and IBD." (PMID 38731999, 2024). "The proportion of DRG neurons expressing TRPV1 in a DSS colitis model and their relative mRNA levels were shown to increase with the subsequent increased release of CGRP and SP." (PMID 38731999, 2024). "This functional difference is also reflected by a TRPV1-mediated promotion but a TRPA1-mediated inhibition of experimental colitis in mice." (PMID 36459135, 2023). "Similar manifestations were found in inflammatory bowel disease (IBD) mice, where activation of TRPV1 promoted DCs recruitment and activation compared to TRPV1-/-, exacerbating the colitis manifestations of the model." (PMID 37744324, 2023). "TRPV1 expression is increased in DRGs projecting to the distal colon when compared to that in the proximal colon, which is also further enhanced during colitis." (PMID 36459135, 2023).